PNPLA3 (patatin like domain 3, 1-acylglycerol-3-phosphate O-acyltransferase )
Diseases named in the same sentence as PNPLA3 in open-access papers (continued):
Sharing a sentence is not in itself a finding about the gene and the disease.
Insulin resistance (continued). "inferred a robust association between PNPLA3 variants and fatty liver, independent of insulin resistance, indicating that these two characteristics are distinct entities." (PMID 38523778, 2024). "It has been found that variants in PNPLA3 is strongly associated with NAFLD in the absence of insulin resistance or dyslipidemia." (PMID 36438727, 2022). "Previous experiments have shown that PNPLA3 I148M does not seem to cause high liver fat content and insulin resistance 35, 82, and recent research showed a deeper relationship." (PMID 34476007, 2021). "This retention of C20:5 could, in addition, protect PNPLA3 148MM carriers from insulin resistance, as saturated fat appears to be more harmful for the liver." (PMID 33557317, 2021). "Serum triglycerides (TG) levels are either the same or lower in PNPLA3-I148M carriers compared to non-carriers, consistent with a lack of association with insulin resistance." (PMID 29286303, 2017). "The impact of the PNPLA3 genotype on insulin resistance is controversial." (PMID 26346943, 2015). "These include the Patatin-like phosholipase domain-containing 3 (PNPLA3) gene variant I148M as a major determinant of inter-individual and ethnicity-related differences in hepatic fat content independent of insulin resistance and serum lipid concentration." (PMID 23394097, 2013). "Our results suggest a possible association between the PNPLA3 148M allele and insulin resistance as well as baseline viral load in HCV genotype 2, but not in genotype 3." (PMID 22978414, 2012). "Our results suggest an association between the PNPLA3 148M allele and insulin resistance as well as viral load in HCV genotype 2, but not genotype 3 infected individuals." (PMID 22978414, 2012). "The PNPLA3 rs738409 GG genotype significantly increased not only cholesterol but also HOMA-IR over 4 years, suggesting that the increase in BMI may have been caused by worsening insulin resistance." (PMID 40074353, 2025). "Next, transcriptomic analysis in obese individuals showed that insulin resistance, carriage of p.I148M and female sex independently correlated with higher PNPLA3 expression, suggesting the mechanism amplifying the phenotype in women may be related to more abundant p.I148M accumulation." (PMID 38224202, 2024). "Moreover, lower levels of adiponectin, an anti-inflammatory cytokine inversely associated with NAFLD, insulin-resistance, and impairment in glucose and lipid metabolism, have been found in both PNPLA3 GG subjects and obese patients, even without NAFLD." (PMID 35276911, 2022). "The protein encoded by this gene—patatin-like phospholipase domain-containing protein 3 (PNPLA3), or adiponutrin—is a lipase that mediates triacylglycerol hydrolysis in adipocytes and hepatocytes; its expression is induced in the liver after feeding and during insulin resistance." (PMID 35328081, 2022). "However, there are also some studies showing a significant relationship between PNPLA3 I148M polymorphism and greater insulin resistance in nonobese individuals from Taiwan and South Korea." (PMID 33102799, 2020). "The PNPLA3-I148M do not show an association of high liver fat content with insulin resistance." (PMID 31062641, 2019). "Although a few studies have hypothesized an association between the PNPLA3 I148M variant and MS, for example mediated by insulin resistance, other studies have failed to confirm this." (PMID 30189691, 2018). "Notably, while the variant is associated with increased liver fat content, PNPLA3-I148M appears not to be associated with other features of metabolic syndrome, like insulin resistance." (PMID 29286303, 2017). "Thus, the association with inflammation and fibrosis is likely independent of lipid accumulation and insulin resistance, and also of any other lipid-related variants such as PNPLA3 and TM6SF2." (PMID 27630043, 2016).
Insulin resistance (continued). "However, it is unclear whether PNPLA3 functions as a lipase or a lipogenic enzyme and whether PNPLA3 is involved in the pathogenesis of hepatic insulin resistance." (PMID 23175050, 2013). "This difference in insulin resistance was seen in the individuals without diabetes but was also reflected in an observed 15% increased risk for type 2 diabetes in the pre-surgery SOS study participants for each PNPLA3 148M allele." (PMID 22724004, 2012). "The dramatically lower transcript levels of ELOVL6 as well as PNPLA3 in hyperinsulinemic insulin-resistant subjects might have an impact to adipocyte lipid composition and could further decline adipose tissue function in insulin resistance." (PMID 22471940, 2012). "We expanded the knowledge about the lack of association between the polymorphism and insulin resistance investigating whether the PNPLA3 148M allele was associated with insulin sensitivity estimated from OGTT." (PMID 22140488, 2011). "Insulin resistance, diabetes mellitus, and genetic variations in transmembrane 6 superfamily member 2 (TM6SF2) and patatin-like phospholipase domain containing 3 (PNPLA3) play important roles in NAFLD progression." (PMID 36188561, 2022). "Emerging evidence supports genetic determinants of FLD (eg PNPLA3, TM6SF2, MBOAT7, GCKR, HSD17B13) as determinants of insulin resistance and T2D." (PMID 33102799, 2020). "In summary, neither PNPLA3 nor TM6SF2 remained independent risk factors per se, but were dependent on the presence of alcohol consumption, higher BMI or insulin resistance." (PMID 41492318, 2026). "Similarly, we have shown that a combination of PNPLA3 and TM6SF2 genotype along with a lipoprotein-derived assessment of insulin resistance was able to predict both NAFLD activity and fibrosis (unpublished data)." (PMID 30355853, 2018). "Actions of PNPLA3 SNPs in BMI, FBG, and insulin resistance (IR) remain controversial until now." (PMID 28695131, 2017). "Whilst insulin resistance both in peripheral tissues and within the liver contributes to this, the evidence from studies looking at PNPLA3 demonstrates that insulin resistance is not an absolute requirement for the development NAFLD." (PMID 26856933, 2016). "The genetic variants in PNPLA3 and TM6SF2 are only responsible for ~50% of NAFLD patients, and majority of PNPLA3-associated NAFLD patients are not obese and have no insulin resistance and its related diabetes and cardiovascular diseases." (PMID 27247565, 2016). "Similarly, the relative small sample size of HCV genotype 2 infected patients in the present study may have contributed to the lack of association of the PNPLA3 148M allele with therapeutic outcome despite its effect on baseline viral load and insulin resistance." (PMID 22978414, 2012). "Notably, patients who had the PNPLA3 rs738409 non-CC genotype had greater insulin resistance than those with the CC genotype, regardless of the TM6SF2 genotype." (PMID 37400794, 2023). "While “Obese/Metabolic NAFLD” is associated with NAFLD and features of the MetS and an increased risk of type 2 diabetes and cardiovascular disease, NAFLD caused by I148M variant in PNPLA3 and the E167K variant in TM6SF2 is not accompanied by insulin resistance." (PMID 27128911, 2016). "While the PNPLA3 or TM6SF2 variants increase liver fat content and the risk of NASH, they do not increase the risk of type 2 diabetes or cardiovascular disease (CVD), consistent with lack of insulin resistance." (PMID 26556368, 2015). "These genes include Patatin-like phospholipase domain containing 3 (PNPLA3), glucokinase regulatory protein (GCKR), and transmembrane 6 superfamily member 2 (TM6SF2), and are independent of insulin resistance." (PMID 37299398, 2023).
diabetes (93 papers, 2011 to 2026). "Extending our previous observations, we found that the excess of CLD among APOB variant carriers was independent from age, sex, BMI, diabetes, alcohol intake and PNPLA3 genotype status." (PMID 41549954, 2026). "Using UK Biobank data, we analysed 241 APOB loss‐of‐function (LoF) carriers and 410 721 non‐carriers, stratified by steatogenic risk factors, including age, sex, diabetes, BMI, alcohol intake and the PNPLA3‐rs738409 genotype." (PMID 41549954, 2026). "Cross‐sectional studies in a relatively small cohort of patients with diabetes and a large cohort of children reported a direct association between the PNPLA3 rs738409 C > G variant and lower estimated glomerular filtration rate (eGFR)." (PMID 39412170, 2025). "When further adjusting the ORs for diabetes, the associations for the PNPLA3 GG genotype and the HSD17B13 TATA genotype remained statistically significant." (PMID 40995436, 2025). "In other words, the presence of diabetes and at-risk PNPLA3 genotype elevated one’s risk category beyond what was predicted by FIB4 alone." (PMID 39774697, 2025). "The bacterial genera, PNPLA3 polymorphisms, old age, and diabetes were independently associated with advanced fibrosis in multivariable analyses." (PMID 38931155, 2024). "After adjusting for the risk factors (age, sex, BMI, WC, HDL, TG, diabetes mellitus, and hypertension), the association of PNPLA3 rs738409 C>G with MASLD remained statistically significant with an increased odds ratio." (PMID 38674389, 2024). "This analysis was based on factors such as age, sex, alcohol consumption, smoking, BMI, hypertension, diabetes, dyslipidemia and metabolic syndrome, and the presence of PNPLA3 rs738409/TM6SF2 rs58542926 variants." (PMID 38862964, 2024). "In a previous study, multivariate analysis showed that age, male sex, diabetes, platelet count, gamma‐glutamyltransferase and albumin levels, and the 7‐SNP genetic risk score, including PNPLA3 and HSD17B13, are independent risk factors of HCC development." (PMID 37644826, 2023). "In the univariate model, we detected a trend for protection against NASH conferred by the MTARC1 polymorphism (p = 0.08), whereas the PNPLA3 variant, hyperlipidemia, and diabetes were all associated with a significantly increased risk of NASH." (PMID 36555467, 2022). "In a multivariate model including the PNPLA3 variant, hyperlipidemia, and diabetes, only the first two proved to represent independent risk factors for non-alcoholic steatohepatitis." (PMID 36555467, 2022). "In this population of subjects with diabetes, the results confirmed the influence of the PNPLA3 polymorphism on the hepatic triglyceride content." (PMID 34833467, 2021). "Although the PNPLA3 gene variant is associated with a disproportionate development of NAFLD and diabetes, the presence of diabetes in the PNPLA3 gene variant carriers still can amplify the genetic effect to drive the progression of NAFLD." (PMID 31447675, 2019). "Similarly, the same group, in a small sample of post‐menopausal females with diabetes, and during a 5‐year follow‐up, observed a faster decline in eGFR in those carrying the PNPLA3 G allele concerning wild‐type patients." (PMID 39412170, 2025). "Notably, the PNPLA3 genotype strongly interacts with diabetes and advanced fibrosis to drive risk of hepatic decompensation, for example." (PMID 40166930, 2025). "Similarly, a study on patients with MASLD and diabetes found that the PNPLA3 GG genotype independently predicted a higher risk of liver complications (HCC and oesophageal varices)." (PMID 39412170, 2025). "Subgroup analyses stratified by baseline fibrosis stage, diabetes status, and genetic polymorphisms (particularly PNPLA3, TM6SF2, and HSD17B13 variants) could identify patients most likely to benefit from SGLT2 inhibitor therapy." (PMID 40872510, 2025).
diabetes (continued). "They argued that patients with the PNPLA3 CC genotype appeared to have higher fasting plasma glucose and rates of type 2 diabetes mellitus, which might explain their higher CVD risk." (PMID 40244110, 2025). "Advanced fibrosis (F3/4), old age, male gender, low platelets (less than 150,000/μL), high AST, diabetes, and the patatin-like phospholipase domain-containing protein 3 (PNPLA3) single nucleotide polymorphism (SNP) GG homozygote have been established as carcinogenic risk factors in Japan." (PMID 32785100, 2020). "They showed that the PNPLA3 I148M genetic variant was strongly associated with increased liver fat content, and that the association remained highly significant after adjusting for BMI, diabetes, ethanol intake, and global and local ancestry." (PMID 30189691, 2018). "Finally, we characterized the presence of the identified risk factors (diabetes, central obesity, hepatitis C, excess alcohol consumption, and 2 PNPLA3 risk alleles) in each of the individuals that had APRI≥1." (PMID 26950933, 2016). "Further, we explored a multifactorial model in a subgroup of participants with genetic data, jointly assessing the predictive accuracy of age, sex, race, diabetes mellitus, PNPLA3-rs738409, and the 55 CpGs." (PMID 40275933, 2025). "Patients of all PNPLA3 genotypes exhibited comparable age, sex distribution, and diabetes prevalence." (PMID 40677694, 2025). "For patients with diabetes and NAFLD, on the one hand, the PNPLA3 gene rs738409 C>G polymorphism increased the risk of cardiovascular disease, on the other hand, it can play a beneficial role in blood glucose control." (PMID 34476007, 2021). "Model 6, which included age, sex, PNPLA3 genotype, diabetes and metabolic syndrome was able to estimate case/control status 72% of the time (95% CI = 64–80%)." (PMID 34629052, 2021). "Of note, the AUROC analysis indicates that no single lipid predicted case/control status better than 71% accuracy after adjusting for age, sex, PNPLA3 genotype, diabetes and metabolic syndrome." (PMID 34629052, 2021). "The pool size of CE was also lower in NAFLD cases compared to controls, after adjusting for covariates such as age, sex, BMI, diabetes, metabolic syndrome status, and PNPLA3 genotype." (PMID 34629052, 2021). "Lipid species that were significantly different between cases and controls after adjusting for age, sex, diabetes, metabolic syndrome status, and PNPLA3 genotype are presented above the black line (P < 0.05)." (PMID 34629052, 2021). "The LPC and SM pools were also decreased even after adjusting for age, sex and PNPLA3 genotype, however, after additionally adjusting for BMI, diabetes and metabolic syndrome, this significance was lost." (PMID 34629052, 2021). "After adjusting for age, sex, diabetes, metabolic syndrome status, and PNPLA3 genotype, a total of 94 lipids were significantly different between cases and controls (P < 0.05, lipids presented above black bar)." (PMID 34629052, 2021). "Analysis of covariance (ANCOVA) was used to compare the overall lipid subclass concentrations between the NAFLD cases and healthy controls, adjusting for appropriate covariates such as age, sex, BMI, diabetes, metabolic syndrome status, and PNPLA3 genotype." (PMID 34629052, 2021). "Adding other covariates, including age, sex, PNPLA3 genotype, diabetes, and metabolic syndrome to the panel of lipids further improved prediction to between 81% (95% CI = 75–88%) and 83% (95% CI = 77–89%)." (PMID 34629052, 2021). "This relationship was replicated in the validation and combined cohorts, and was independent of confounding factors including age, gender, BMI, presence of diabetes and PNPLA3 phenotype." (PMID 26462272, 2015). "Even after controlling for traditional risk factors such as diabetes mellitus and metabolic syndrome, Mexican Hispanics still had a higher likelihood of NAFLD, with genetic differences, particularly the PNPLA3 gene, explaining up to 72% of the racial difference in NAFLD prevalence." (PMID 40295270, 2025).
diabetes (continued). "Another study of NAFLD patients who did not have diabetes and were not obese showed that PNPLA3 rs738409 I148M increased the risk for CKD, but TM6SF2 rs58542926 E167K reduced the risk for CKD." (PMID 37400794, 2023). "Our results suggest that PNPLA3 does not independently influence cardiovascular risk in patients with type 2 diabetes mellitus." (PMID 34833467, 2021). "The coexistence of PNPLA3 G allele and HSD17B13 major allele homozygosity is an unfavourable, high-risk genetic profile for HCC, which is independent from alcohol abuse, degree of fibrosis, and diagnosis of diabetes mellitus." (PMID 32382265, 2020). "Therefore, the PNPLA3 rs738409 C > G variant provides an example of a disproportionate progression of NAFLD and diabetes." (PMID 31447675, 2019). "In females, an additive effect between central obesity and 2 PNPLA3 risk alleles was observed with 51.2% showing both risks regardless of the presence of diabetes." (PMID 26950933, 2016). "In this study, the genetic variant of Patatin-like phospholipase domain-containing 3 (PNPLA3), rs738409, also known as I148M, was associated with greater lipid contents, even after adjustments for the ethnicity, body mass index (BMI), diabetes status, and alcohol intake." (PMID 36672614, 2022). "However, it is still unknown whether the relationship of NAFLD with PNPLA3 variant exists or not among subjects with type 2 diabetes mellitus (T2DM)." (PMID 35486295, 2022). "Several genes encoding proteins known to be related to cholesterol metabolism and transport (CYP7A1, HMGCR) and genes involved in non-insulin dependent diabetes mellitus (GCK, PNPLA3) were down-regulated 3- to 23-fold." (PMID 26442469, 2015). "Importantly, eight MASLD patients harbored both GG (PNPLA3) and TT (ABCC8) genotype, and all were known cases of diabetes, suggesting a synergistic genetic interaction." (PMID 40981175, 2025). "Conversely, a longitudinal study on 407 patients with diabetes and MASLD found a reduced risk of extrahepatic cancers in patients with PNPLA3 CG genotype respect to CC wild‐type, but not in GG homozygous." (PMID 39412170, 2025). "According to univariate logistic regression analysis, several factors were significantly associated with MASLD (p < 0.005): arterial hypertension, prediabetes, or diabetes mellitus, decreased HDL, hypertriglyceridemia, the PNPLA3 rs738409 GC/GG genotype, and the PNPLA3 rs2896019 TG/GG genotype." (PMID 40864759, 2025). "Of note, the PNPLA3 polymorphism is associated with a 3-fold increased risk of HCC in its carriers, independent of other risk factors such as BMI, diabetes, and advanced fibrosis." (PMID 38672997, 2024). "Recommended diet decreased f-BA in all subjects regardless of the PNPLA3 genotype, and f-BA did not correlate with clinical characteristics, diabetes indices (our study subjects were non-diabetic) or NAFLD-related scores." (PMID 38257154, 2024). "It correlates with the extent of steatosis and progression of fibrosis in MASH, independent of obesity, diabetes, and the PNPLA3 genotype." (PMID 38672997, 2024). "Addition of genetic markers for the prediction of advanced fibrosis (baseline model: age, sex, BMI, diabetes: AUC 0.777) resulted in a higher AUC if PNPLA3(AUC 0.789), and TM6SF2(AUC 0.786) but not if HSD17B13(0.777) were added." (PMID 34076851, 2021). "The TM6SF2 gene variant is associated with increased risks of NAFLD, NASH, and advanced fibrosis independent of age, body mass index (BMI), presence of diabetes, and PNPLA3 genotype status." (PMID 31447675, 2019). "In our study where vast majority of patients did not have diabetes, PNPLA3 genotype was a significant factor of fibrosis progression." (PMID 26352693, 2015). "Similarly, the PNPLA3 genotype does not influence the prevalence of diabetes and incidence of new-onset diabetes." (PMID 33923295, 2021). "Prediabetes or DM, hypertriglyceridemia, and the PNPLA3 rs2896019 TG/GG genotype did not demonstrate statistical significance in this model." (PMID 40864759, 2025).
diabetes (continued). "In particular, this score which included PNPLA3 and TM6SF2 genotypes, IR, diabetes, hepatic enzymes and C-reactive protein and it was able to detect NASH with an AUROC of 0.835 (95% CI, 0.776–0.895) and of 0.809 (95% CI, 0.757–0.861) in NAFLD patients with and without diabetes, respectively." (PMID 34680476, 2021).